RN7SL478P (RNA, 7SL, cytoplasmic 478, pseudogene)
Gene: Miscellaneous RNA gene on chromosome 7 (97,998,325 to 97,998,622, forward strand). Ensembl gene ENSG00000277946.
Homologues: Orthologues: chimpanzee Metazoa_SRP (99% identical), macaque Metazoa_SRP (92% identical). Paralogues in human: RN7SL556P (97% identical), RN7SL1 (87% identical), RN7SL2 (87% identical), RN7SL3 (86% identical), RN7SL14P (83% identical), RN7SL220P (83% identical), RN7SL296P (83% identical), RN7SL655P (83% identical), RN7SL451P (83% identical), RN7SL566P (83% identical), RN7SL126P (82% identical), RN7SL448P (82% identical), and 704 more.